IGF2BP1 (insulin like growth factor 2 mRNA binding protein 1)
Diseases named in the same sentence as IGF2BP1 in open-access papers (continued):
Sharing a sentence is not in itself a finding about the gene and the disease.
ovarian carcinoma (continued). "We also executed correlation analysis using proteome datasets by mining the functional partners of IGF2BP1, as it has been shown that MMP family members were downregulated by IGF2BP1 silencing in ovarian carcinoma, thus reducing the invasive nature of tumor." (PMID 36092925, 2022). "In osteosarcoma-derived U2OS and ovarian carcinoma-derived ES-2 cells, decreased MAPK4 mRNA translation mediates the prometastatic effect of IGF2BP1, suggesting that MAPK4 acts as a tumour suppressor." (PMID 36618768, 2022). "For example, IGF2BP2 gene is a relatively common event in comparison to the amplification of the other IGF2BPs family members, IGF2BP1 and IGF2BP3, occurring in ~15–27% of ovarian cancers." (PMID 35717493, 2022). "We demonstrated four immune infiltration‐related m6A regulators in ovarian cancer, including RBM15B, ZC3H13, YTHDF1, and IGF2BP1." (PMID 33225598, 2021). "In agreement, there is a significant and conservative correlation between IGF2BP1 and SRF expression in ovarian cancer." (PMID 34794452, 2021). "Importantly, our data showed that immune cell infiltration levels and various immune gene markers were closely associated with the expression of m6A regulators, suggesting that RBM15B, ZC3H13, YTHDF1, and IGF2BP1 might play the role of immune infiltration‐related m6A regulators in ovarian cancer." (PMID 33225598, 2021). "For example, IGF2BP1, a positive-reader that enhances mRNA stability and storage, promotes the expression of oncogene SRF in an m6A-dependent manner in ovarian cancer." (PMID 32998774, 2020). "In these conditions, IGF2BP1, LIN28B and HMGA2 form a partially self-sustaining oncogenic triangle, where HMGA2 enhances cell growth, and IGF2BP1 and LIN28B promote the migratory and self-renewal potential of ovarian cancer cells." (PMID 31434359, 2019). "Interaction of IGF2BP1 with c-MYC mRNA inhibits CRD-dependent mRNA decay and is correlated with poor prognosis in ovarian carcinoma." (PMID 27588393, 2016). "Except ovarian carcinoma-derived OVCAR cells, which expressed CDH1 and KRT8 but barely any of the analyzed mesenchymal markers, significant IGF2BP1 expression was only observed in mesenchymal-like tumor- or metastases-derived cells." (PMID 23677615, 2013). "Meanwhile, compounds 7773 and C20H18BrN5OS could suppress cell growth and migration potentials by obstructing IGF2BP1-dependent post-transcriptional stabilization of MYC mRNA in NSCLC, ovarian clear cell carcinoma, and ovarian cancer." (PMID 40584294, 2025). "BTYNB specifically targets and inhibits cell proliferation of IGF2BP1‐positive cells but not IGF2BP1‐negative cells in melanoma and ovarian cancer cell lines." (PMID 38545841, 2024). "This research confirmed that CACNA1G-AS1 is obviously upregulated in ovarian cancer samples and could upregulate FTH1 through IGF2BP1-mediated m6A methylation." (PMID 37304234, 2023). "Ferritinophagy and ferroptosis-related indicator detection showed that CACNA1G-AS1/IGF2BP1-mediated FTH1 m6A methylation could inhibit ferritinophagy and ferroptosis in ovarian cancer cells." (PMID 37304234, 2023). "LncRNA ubiquitination modifier activator 6 antisense RNA1 (UBA6-AS1) recruits RBM15 to mediate UBA6 m6A methylation, and IGF2BP1 enhances UBA6 stability by recognizing its m6A modification, ultimately encouraging ovarian cancer cell proliferation, invasion, and migration." (PMID 37194218, 2023). "In fact, IGF2BP1 has been found to be frequently overexpressed in many cancers, such as head and neck squamous cell carcinoma (HNSCC), melanoma, cervical cancer, ovarian carcinoma and lung cancer." (PMID 36092925, 2022). "Two GEO databases demonstrated that 7 readers (HNRNPC, IGF2BP1, IGF2BP2, IGF2BP3, RBMX, YTHDC2, and YTHDF2) and 3 writers (METTL3, RBM15, and RBM15B) were more highly expressed in ovarian cancer than in ovarian surface epithelium or normal peritoneum tissues (GEO14407 and GEO12470)." (PMID 33225598, 2021).
ovarian carcinoma (continued). "In particular, we could show that IGF2BP1 shields the transcripts of LIN28B and HMGA2 as well as its own mRNA from let-7-mediated downregulation in ovarian cancer-derived cells, thus promoting an aggressive tumor phenotype." (PMID 32545414, 2020). "In ovarian cancer, elevated expression of the ‘oncogenic gene set’ comprising IGF2BP1, SRF, FOXK1 and PDLIM7 was not significantly (P = 0.077) associated with poor overall survival (OS) but showed the expected trend with a HR of 1.22." (PMID 30371874, 2019). "Interestingly, the autoantibody against IGF2BP1 was also detected at a comparable percentage (26.5%), and it is unknown whether the autoimmune responses to IGF2BP1 and IGF2BP2 are correlated in ovarian cancer patients." (PMID 29736175, 2018). "In our research, the regulatory mechanism of IGF2BP1-mediated FTH1 methylation in this process and the relationship between ferroptosis and mitophagy in ovarian cancer cells were not fully elucidated, and these topics need to be further explored with subsequent experiments." (PMID 37304234, 2023).
melanoma (43 papers, 2013 to 2026). A malignant, usually aggressive tumor composed of atypical, neoplastic melanocytes. "Our retrospective data analysis of immunotherapies in human melanoma patients indicates that high levels of IGF2BP1 and IGF2BP3 are associated with resistance to immunotherapies and poor prognosis." (PMID 37503349, 2023). "Analysis of data from human melanoma patients indicates that high levels of IGF2BP1 and IGF2BP3 are associated with resistance to immunotherapies and poor survival." (PMID 37503349, 2023). "Increased immunogenicity, associated with Igf2bp1 inhibition, “inflames” mouse melanoma tumors microenvironment in SM1/C57BL/6 and SW1/C3H mouse models measured by a two-fold increase of NK cells and tumor-associated myeloid cells." (PMID 37503349, 2023). "This mirrors findings in syngeneic melanoma models where Igf2bp1 knockdown enhanced ICT responsiveness. scRNA-seq analysis revealed that BT boosts immune infiltration and reactivation beyond that achieved by PD-1 blockade alone." (PMID 41444249, 2025). "Specifically, the downregulation of IGF2BP1 in melanoma cells was shown to bolster the growth‐inhibitory influence of IFN signals and enhance the susceptibility of tumors to anti‐PD1 treatment in both murine and human melanoma models." (PMID 40672434, 2025). "shRNA-mediated knockdown of IGF2BP1 in melanoma, neuroblastoma, and CRC cell lines increases sensitivity to a variety of chemotherapeutic drugs, and IGF2BP1 expression is elevated in chemoresistant CRC tumors." (PMID 40629079, 2025). "The depletion of IGF2BP1 reduces melanoma metastasis and enhances the sensitivity of melanoma to targeted therapy." (PMID 40483535, 2025). "The increased number of immune cells can be explained by the enhanced expression of pro-inflammatory genes and the increased presentation of mouse MHC I (H-2) complex on Igf2bp1-depleted melanoma cells." (PMID 37503349, 2023). "The inhibitory effect of both mrIfn-β and mrIfn-γ in Igf2bp1 gene knockout cells was rescued by Ifnar1 knockout in melanoma cell line PVMM, which shares a genetic background with the wild type SM1 cell line." (PMID 37503349, 2023). "We also observed an increase in the CD45.2+/Ly6G-/Ly6C+ myeloid subset in the tumor microenvironment of SM1/Igf2bp1-KO melanoma mouse model." (PMID 37503349, 2023). "Flow cytometric analysis of myeloid and lymphoid cells extracted from C57BL/6 mouse melanoma model using SM1 Igf2bp1-KO and CRISPR/Cas9 control showed increased accumulation of some immune cell subsets in the tumor microenvironment." (PMID 37503349, 2023). "Genetic inhibition of Igf2bp1 provokes accumulation of lymphoid and myeloid cells in the tumor microenvironment in mouse melanoma models." (PMID 37503349, 2023). "We have found that patients with high expression levels of IGF2BP1 and IGF2BP3 have statistically significant poorer survival rates compared to those whose melanoma cells had low IGF2BP1 and IGF2BP3 levels." (PMID 37503349, 2023). "EVs (extracellular vesicles) from IGF2BP1-overexpressed melanoma cells further accelerated EV-induced metastasis." (PMID 35935853, 2022). "CDR1as is downregulated in cutaneous melanoma and regulates the metastatic phenotype of melanoma by interacting with IGF2BP1 instead of binding to miR-7." (PMID 35534866, 2022). "And EVs from IGF2BP1 knockdown melanoma cells affected the metastasis microenvironment via inhibiting fibronectin deposition and CD45+ cell accumulation in the lung; thus, EVs from IGF2BP1 knockdown melanoma cells cannot promote metastasis." (PMID 35935853, 2022). "It is reported that IGF2BP1 accelerated melanoma cell metastasis and target inhibition enhances the effects of BRAF-inhibitor and BRAF-MEK inhibitors in BRAF mutation melanoma." (PMID 35722625, 2022). "p62 interacted with IGF2BP1 via the PB1 domain in UACC-62 cells (melanoma cell lines) and then controlled the mRNA stability of FERMT2 and multiple pro-metastatic factors (EHMT2, CD2AP, TOP2A, FLOT1, OGFOD1, and NCEH1)." (PMID 35935853, 2022).
melanoma (continued). "Insulin-like growth factor 2 mRNA-binding protein 1 is rich in melanoma cell EVs and promotes PMN formation in the lungs through the deposition of fibronectin and accumulation of CD45+ cells." (PMID 34616739, 2021). "Previous work has demonstrated that knocking down or inhibiting IGF2BP1 in some cancers such as melanoma sensitizes the cells to chemotherapeutic and targeted agents." (PMID 33796454, 2021). "Though knockdown or inhibition of IGF2BP1 has been shown to sensitize melanoma to some chemotherapeutic agents and targeted therapy, its role as a potential therapeutic target in treating neuroblastoma has not been investigated." (PMID 33796454, 2021). "Of note, several of the other genes with decreased expression upon knockdown of Tfap2a have been reported in the literature as activated (Aldh1a3, Igf2bp1, Ephb2, Pbk) or downregulated (Qpct, Wfdc1) in melanoma." (PMID 28249010, 2017). "Furthermore, our results were consistent with a previous study on melanoma, where patients treated with PD-1 antibody immunotherapy exhibited significantly decreased IGF2BP1 expression after treatment." (PMID 40088376, 2025). "In neuroblastoma and melanoma, IGF2BP1 promotes tumor metastasis by regulating the cargo of EVs." (PMID 40584294, 2025). "Moreover, another study indicated that the expression of IGF2BP1 impacts the responsiveness of melanoma cells to dabrafenib and trametinib." (PMID 40088376, 2025). "Indeed, genetic downregulation of IGF2BP1 sensitizes melanoma cells for both targeted therapy and immunotherapy." (PMID 40629079, 2025). "In the hypoxic TME, hypoxia enhances IGF2BP1 expression levels by regulating the ability of hypoxia-inducible factor-1alpha (HIF-1α to bind to the IGF2BP1 promoter, subsequently increasing the proliferation and invasion potentials of melanoma cells, while decreasing their apoptotic rates." (PMID 40584294, 2025). "In addition, we analyzed the expression changes of IGF2BP1/2/3 in melanoma and glioblastoma patients before and after anti-PDL1 immunotherapy through multiple SRA datasets." (PMID 40088376, 2025). "Similarly, inhibition of IGF2BP1 inhibited cell proliferation, thereby slowing ovarian cancer and melanoma progression." (PMID 39033180, 2024). "Finally, in limited adult tissues, increased expression of the insulin-like growth factor 2 mRNA-binding protein 1 (IGF2BP1) gene has been reported in cancers, including gastrointestinal cancers, lung cancer, melanoma, and colorectal cancer." (PMID 39028420, 2024). "Since the IGF2BP3 paralogue IGF2BP1 was reported to be loaded in EVs derived from metastatic pancreatic and melanoma cells, we examined whether IGF2BP3 was released by EWS cells into the supernatants as a free soluble molecule or loaded into EVs." (PMID 37353558, 2023). "Indeed, mouse melanoma cells with Igf2bp1, 2 and 3 knockouts demonstrated the increased expression of H-2Db and H-2Kb MHC I, enhancing a cell capacity of inducing intracellular Ifn-γ expression in syngeneic T-lymphocytes." (PMID 37503349, 2023). "Finally, we demonstrate that the efficiency of anti-PD1 immunotherapy in the mouse melanoma model is significantly more efficient in tumors that lack Igf2bp1 expression." (PMID 37503349, 2023). "Finally, our mouse melanoma model of anti-PD1 immunotherapies showed a significant increase of mouse survival when PD-1 inhibition is combined with inhibition of Igf2bp1." (PMID 37503349, 2023). "To further investigate the physiological significance of IGF2BPs proteins in innate and adaptive immune responses in melanoma, we created Igf2bp1, 2, and 3 genes knockouts (-KO) in mouse melanoma cell line SM1 and mouse melanoma B16.F10 cells expressing T antigen (B16.F10-Tag)." (PMID 37503349, 2023). "Similar to human melanoma cell line MEL928, proliferation of mouse SM1 cells was severely impaired by exposure to mouse recombinant interferon beta (mrIfn-β), and almost abolished after mrIfn-β treatment in Igf2bp1 deficient cells." (PMID 37503349, 2023).
melanoma (continued). "In our retrospective analysis of human melanoma patients who received immunotherapy, high levels of IGF2BP1 and IGF2BP3, but not IGF2BP2, were associated with poor clinical outcomes." (PMID 37503349, 2023). "It has been reported that IGF2BP1 may serve as a prognostic marker in melanoma, on account of IGF2BP1 being overexpressed in metastatic melanoma, which leads to resistance to chemotherapeutic agents." (PMID 35935853, 2022). "Additionally, we have shown that inhibition of Igf2bp1 sensitizes melanoma to chemotherapy and targeted therapies." (PMID 34895045, 2022). "IGF2BP1 was closely related to the regulation of the cargo of EVs, thus affecting the pro-metastatic function of melanoma-derived EVs, which may open a new way for the development of potential inhibitors for cancer treatment." (PMID 35935853, 2022). "Besides, knockout of IGF2BP1 alone is sufficient to reduce the tumorigenicity of vemurafenib-resistant melanoma." (PMID 35935853, 2022). "An autophagy-independent role of p62/SQSTM1 has been ascribed to the control of melanoma metastasis by recruiting RNA-binding proteins in cooperation with insulin-like growth factor 2 mRNA-binding protein 1 (IGF2BP1) to stabilize transcripts of a number of pro-metastatic factors." (PMID 32340261, 2020). "Upregulation of IGF2BP1 expression in human melanoma or mouse model was observed." (PMID 29954406, 2018). "However, whether IGF2BP1 promotes melanoma metastasis partly by regulation m6A methylation needs further study." (PMID 35722625, 2022). "The results showed that after immunotherapy, the expression of IGF2BP1/2/3 was significantly downregulated in melanoma and glioblastoma patients, except in the SRP302761 dataset (melanoma)." (PMID 40088376, 2025). "eEF2, an oncogenic translational regulator, becomes a new IGF2BP1 target mRNA, allowing BTYNB to effectively inhibit the proliferation of OC and melanoma cells containing IGF2BP1." (PMID 39062595, 2024). "Two mouse melanoma models used in this study, Igf2bp1-KO in SM1/C57BL/6 and the doxycycline inducible Igf2bp1-KD in SW1/C3H, demonstrated the reduction of tumor’s size and the increased numbers of lymphoid and myeloid immune cells present in those tumors." (PMID 37503349, 2023). "Inhibition of IGF2BP1 can enhance the role of BRAF inhibitors and BRAF-MEK inhibitors in BRAFV600E melanoma." (PMID 35935853, 2022). "Inhibition of IGF2BP1 can reduce the stability of PKCα mRNA, the expression of PKCα protein, and MAPK/ERK activation to improve overall survival in melanoma." (PMID 35935853, 2022). "IGF2BP1 stabilized MITF mRNA and increased its expression and its transcriptional activity in melanoma, which was mediated by counteracting the miR-340–mediated degradation of MITF mRNA." (PMID 35935853, 2022). "Inhibition of IGF2BP1 expression further promoted the treatment efficacy of a BRAF inhibitor and reduced the tumorigenicity of vemurafenib-resistant melanoma cells." (PMID 34203267, 2021). "Thus, IGF2BP1 could be a reduce-chemoresistance target for melanoma." (PMID 29954406, 2018). "In addition to CSDE1, several RBPs have been shown to play roles in melanoma progression, including CELF, CPEB4, IGF2BP1, IGF2BP3, NOVA1 and DDX3X, among others." (PMID 38396995, 2024). "Interestingly, recent animal research also found that in melanoma, inhibiting IGF2BP1 expression affected CD45 levels and then PMN formation, significantly reducing the probability of EVs-mediated lung metastasis in melanoma." (PMID 39033180, 2024). "In addition, the conservative interaction between THOR and IGF2BP1 has been reported, and it has been shown that THOR was conducive to the mRNA stabilization activities of IGF2BP1 in the zebrafish model of melanoma." (PMID 35935853, 2022).
melanoma (continued). "We have recently demonstrated that Igf2bp1 can cooperate in the induction of lung adenocarcinoma (LUAD) and melanoma metastasis, and down-regulation of Igf2bp1 severely inhibits metastasis in diverse immunocompetent mouse models of LUAD and melanoma progression." (PMID 34895045, 2022). "Comparing primary melanoma and metastases, we found that ALKBH5, ELAVL1, FMR1, HNRNPA2B1, HNRNPC, IGF2BP1/2/3, KIAA1429, LRPPRC, RBM15, YTHDC1/2, YTHDF1/3, and ZC3H13 were significantly upregulated in metastases, while RBM15B and METTL3 were significantly upregulated in primary melanoma." (PMID 34993195, 2021). "Similar to IGF2BP1, IGF2BP3 expression correlates with a poor prognosis and tumor aggressiveness in several cancers including gastrointestinal cancers, lung cancer, and melanoma." (PMID 34203267, 2021). "Moreover, IGF2BP1 knockdown was found to reduce levels of c-MYC, which contributes to the suppression of NF-kB activity and of anchorage-independent growth of melanoma cells and proliferation, as well as induces apoptosis." (PMID 29954406, 2018).